PTCD2 (pentatricopeptide repeat domain 2)
Description:
Involved in mitochondrial RNA maturation and mitochondrial respiratory chain function.
Synonyms: FLJ12598
Tractability: PROTAC: ubiquitination databases record sites on it; its protein half-life has been measured.
Gene: Protein-coding gene on chromosome 5 (72,320,318 to 72,368,395, forward strand). Ensembl gene ENSG00000049883.
Subcellular location: Mitochondrion
Gene Ontology:
Molecular function: protein binding; RNA binding
Biological process: mitochondrion organization; regulation of mRNA processing
Cellular component: mitochondrion
Genetic constraint (gnomAD): Loss-of-function variants: 6 observed, 14.85 expected, observed/expected ratio (o/e) 0.4, 90% interval 0.22 to 0.8. The upper end of that interval is the gene's LOEUF score, 0.8, which puts it in group 3 of 6, group 1 being the genes least tolerant of losing a copy. Missense variants: 270 observed, 236.17 expected, observed/expected ratio (o/e) 1.14, 90% interval 1.03 to 1.26. Synonymous variants: 112 observed, 100.05 expected, observed/expected ratio (o/e) 1.12, 90% interval 0.96 to 1.31.
Homologues: Orthologues: chimpanzee PTCD2 (99% identical), macaque PTCD2 (87% identical), pig PTCD2 (81% identical), dog PTCD2 (76% identical), guinea pig PTCD2 (74% identical), rat Ptcd2 (73% identical), mouse Ptcd2 (72% identical), tropical clawed frog ptcd2 (49% identical), zebrafish ptcd2 (42% identical).
Diseases named in the same sentence as PTCD2 in open-access papers:
PTCD2 is named in the same sentence as 6 diseases in open-access papers, as found by Europe PMC text mining. Sharing a sentence is not in itself a finding about the gene and the disease. The quoted sentences say what the papers report.
coronary heart disease (1 paper, 2023). "Four of them (CLDND1: Claudin Domain Containing 1, AHRR: Aryl Hydrocarbon Receptor Repressor, MPO: Myeloperoxidase, and PTCD2: Pentatricopeptide Repeat Domain 2), involved in lipid metabolism and inflammatory diseases, were associated with coronary heart disease." (PMID 37190071, 2023).
Hypertension (1 paper, 2021). The presence of chronic increased pressure in the systemic arterial system. "One CpG located within PTCD2 was previously identified to be associated with hypertension in obstructive sleep apnea patients, and genetic variants in this gene have been related with blood pressure." (PMID 33883000, 2021).
cancer (3 papers, 2016 to 2024). A tumor composed of atypical neoplastic, often pleomorphic cells that invade other tissues. "Notably, the levels of expression of these genes, added to six other genes involved in mitochondria activity (TST, NSUN3, GLMP and PTCD2), were reduced following the expression of HLA-G in the RCC7 cells, consistent with mitochondrial impairment found in many types of cancer, particularly in ccRCC." (PMID 39358558, 2024).
PTCD2 also shares sentences with these, for which no sentence is quoted: Alzheimer disease (1 paper); multiple sclerosis (1); obstructive sleep apnea (1).